KIT (KIT proto-oncogene, receptor tyrosine kinase)
Diseases named in the same sentence as KIT in open-access papers (continued):
Sharing a sentence is not in itself a finding about the gene and the disease.
germ cell tumor (continued). "The importance of better understanding the c‐KIT and STRA8 regulation is not only related to spermatogenesis, but extend also to testicular germ cell tumours." (PMID 33236849, 2021). "Imatinib, an inhibitor of several tyrosine kinases, including c-KIT, was evaluated in six patients with KIT-expressing refractory germ cell tumors." (PMID 32485873, 2020). "Most germ cell tumour components are positive for SALL-4 and pan-keratin, whereas seminomatous elements are positive for KIT (CD117) and OCT-4." (PMID 29621151, 2018). "A subset of germ-cell tumors in non-epithelial ovarian malignancies can develop KRAS-activating mutations, as well as other genetic changes such as KIT and MAPK." (PMID 36686734, 2022). "Molecular characterization studies have shown that KIT or KRAS gene mutations are present in about 25% of seminomas, yet it is rare in non-seminomatous germ cell tumor." (PMID 35651799, 2022). "c-KIT is also expressed in human IGCNU contrary to nonseminomatous germ cell tumors and stromal tumors which do not express c-KIT." (PMID 25096628, 2014). "c-KIT was reported to be overexpressed in 48% of chemorefractory non-seminomatous germ cell tumors." (PMID 35740662, 2022). "In addition to pazopanib, two trials suggested the TKI against PDGFR, VEGFR 1–3, c‐KIT, FLT sunitinib to be of clinical benefit in patients with seminomateous or non-seminomateous germ cell tumors refractory to first line therapy." (PMID 29250197, 2017). "Thus, c-KIT-targeted NIR-PIT, whose efficacy was investigated in in vivo gastrointestinal stromal tumor mouse models, may be utilized to treat chemorefractory non-seminomatous germ cell tumors." (PMID 35740662, 2022).
non-small cell lung carcinoma (45 papers, 2007 to 2025). A group of at least three distinct histological types of lung cancer, including non-small cell squamous cell carcinoma, adenocarcinoma, and large cell carcinoma. "In a similar manner, c-KIT expression was associated with lymph node metastasis, histological type, and worse overall survival in human non-small cell lung cancer, according to a meta-analysis." (PMID 36851392, 2023). "For example, EGFR mutations predictive of response to erlotinib and gefitinib were identified at the expected frequency (12%) in non-small cell lung cancer, and KIT mutations linked to sensitivity to imatinib and nilotinib were detected in 76% of GISTs." (PMID 19924296, 2009). "miR-1260b was suggested to directly suppress suppressor of cytokine singling 6 (SOCS6) expression and activate KIT proto-oncogene (KIT) signaling in non-small-cell lung cancer (NSCLC)." (PMID 32252322, 2020). "Recently, anlotinib hydrochloride, a new orally administered tyrosine kinase inhibitor, was found to have extensive advantages in treating non-small cell lung cancer by targeting KIT, VEGFA and FGFR1." (PMID 32427575, 2020). "For instance, elevated KITLG expression contributes to the carcinogenesis of uveal melanoma 18, neurofibromatosis type 1 19, gliomagenesis 20, breast cancer 21 and non-small-cell lung cancer 22, presumably because of the c-KIT/KITLG autocrine/paracrine stimulation-loop mechanism 23,24." (PMID 25213795, 2014). "Tyrosine kinase signaling pathways have been successfully targeted in malignancies, examples include EGFR in non-small cell lung cancer (NSCLC), KIT in gastrointestinal stromal tumors, and ERBB2 breast cancers, to name a few." (PMID 28030802, 2017). "The c-KIT/KITLG axis plays an important role in the self-renewal and proliferation of cancer stem cells in non-small-cell lung cancer." (PMID 25213795, 2014). "The angiokinase inhibitor nintedanib which targets VEGFR, PDGFR, and FGFR is approved for the treatment of non-small-cell lung cancer, idiopathic pulmonary fibrosis, and other lung diseases by the FDA and EMA was identified as a novel KIT D816V inhibitor using this model." (PMID 34063170, 2021).
osteosarcoma (44 papers, 2007 to 2025). A usually aggressive malignant bone-forming mesenchymal neoplasm, predominantly affecting adolescents and young adults. "One sample of osteosarcoma demonstrated a mutation of the KIT gene." (PMID 29541442, 2018). "In the context of human cancer, ovarian and osteosarcoma cancer cells expressing KIT were reported to be chemotherapy resistant and have increased tumorigenicity." (PMID 34718356, 2022). "Although KIT has been widely studied in neoplastic and non-oncological diseases, there are few preclinical and clinical studies on KIT in osteosarcoma." (PMID 32984034, 2020). "In 2011, another study found that KIT was expressed in 46.15% patients with osteosarcoma and that KIT-positive tumors had worse response to chemotherapy." (PMID 32984034, 2020). "For example, SRC kinase, which plays a key role in the development of osteosarcoma, can be activated, respectively by VEGFRs, KIT, RET, PDGFRs, IGF-1R, and AXL." (PMID 32984034, 2020). "Over expression of the KIT gene and resultant increased levels, has previously been identified as a potential therapeutic target in paediatric osteosarcoma." (PMID 29541442, 2018). "Regorafenib an oral multikinase inhibitor targeting angiogenic factors (VEGFR1-3, TIE2), oncogenic kinases (KIT, RET, RAF) and pazopanib inhibiting VEGFR, PDGFR and cKIT are going to be assessed in osteosarcoma." (PMID 29238848, 2018). "However, clinical trials in osteosarcoma have shown that single‐target therapy, such as inhibiting VEGFs (with bevacizumab), KIT and PDGFRα (with imatinib), or IGF‐1R (with cixutumumab or R1507) has limited efficacy." (PMID 40344484, 2025). "Similarly, in bone sarcomas, levantanib, a multi-kinase inhibitor targeting VEGF, FGFR, PDGFR-α, and KIT showed promising preclinical activity in osteosarcoma." (PMID 40983796, 2025). "For example, the activity of imatinib is quite limited in osteosarcoma, suggesting that the inhibition of KIT and PDGFR may be inferior targets." (PMID 34298746, 2021). "The receptors MET, IGF-1R, AXL, PDGFRs, KIT, and FGFRs might be relevant but unimportant RTKs for osteosarcoma." (PMID 32984034, 2020). "The receptor tyrosine kinases (RTKs) MET, IGF-1R, AXL, PDGFRs, KIT, and FGFRs might be relevant but unimportant targets for osteosarcoma treatment." (PMID 32984034, 2020). "However, clinical trials in osteosarcoma have demonstrated the low efficacy of single-target therapy by inhibiting VEGFs (by bevacizumab), KIT and PDGFRα (by imatinib), and IGF-1R (by cixutumumab or R1507)." (PMID 32984034, 2020). "We further showed that KIT, PDGFRs, and FGFRs might be relevant but unimportant RTKs for osteosarcoma." (PMID 32984034, 2020). "Supporting this was the potential importance of angiogenesis in osteosarcoma and Ewing sarcoma, as well as the expression of targetable RTKs such as RET, MET, PDGFR, KIT, AXL, and FGFR." (PMID 34298746, 2021). "Furthermore, genomic sequencing of 71 paediatric and adult osteosarcoma samples reported 20% had an amplification at 4q12 spanning PDGFRA, VEGFR2, and KIT, and in total, 40% of participants had either PDGFRA or VEGF amplification." (PMID 40983796, 2025). "In 2007, a study showed that tumor specimens from 20 out of 100 patients with osteosarcoma were KIT-positive and that OS were not different between patients with and without KIT expression." (PMID 32984034, 2020). "The results of both studies point to the possibility that KIT is not a key player in proliferation and metastasis of osteosarcoma." (PMID 32984034, 2020). "Interestingly, the osteosarcoma T30 was the only tumor showing an amplification of CFA13 containing the oncogenes cMYC and KIT. cMYC amplifications and CFA13 gains have been detected in canine and human cancers before." (PMID 24098698, 2013). "Furthermore, a review of the literature suggests that KIT, PDGFRs, MET, IGF‐1R, and AXL could also serve as potential therapeutic targets for osteosarcoma." (PMID 40344484, 2025).
osteosarcoma (continued). "To test whether DNA replication stress can induce soluble H2AX, we used the human osteosarcoma cell line U-2 OS that, unlike GIST cells, does not depend on a single oncogenically activated tyrosine kinase such as KIT and has bona fide normal DNA damage response pathways." (PMID 18616816, 2008).
metastatic disease (40 papers, 2005 to 2025). "In this case, given our interest in this case’s genotype, we conducted retrospective Sanger sequencing of the resected metastatic tumor during manuscript preparation, revealing coexisting KIT exon 11 (p.W557_K558del) and exon 13 (p.V654A) mutations." (PMID 40590035, 2025). "This association between a cancer-critical mutation in the KIT gene and elevated odds of metastatic disease is supported by previous findings." (PMID 38927753, 2024). "Patients with KIT exon 11 mutated GIST resection of metastatic disease was also associated with significantly longer (63.2 months) median OS compared with patients without palliative surgery (39.5 months)." (PMID 29480823, 2018). "The second patient had a KIT-mutated vulvar melanoma that had been treated surgically before subsequent development of lung metastatic disease." (PMID 28428884, 2017). "Only 4 of those 108 GIST patients for which mutational analysis was performed were diagnosed initially with metastatic disease, 3 of them with mutation in exon 11 of c-KIT gene and 1 wild type GIST." (PMID 25885906, 2015). "Several groups have identified specific mutational subtypes in KIT exon 11 associated with an increased risk of metastatic disease whereas GISTs with PDGFRA mutations often behave less aggressive." (PMID 20598160, 2010). "GISTs may involve mutations in the c-KIT gene, which can guide targeted therapies for unresectable or metastatic disease." (PMID 40091963, 2025). "The metastatic tumor was excised in the Affiliated Cancer Hospital of Zhengzhou University at the size of 7 × 6 × 6 cm and was pathologically diagnosed with GISTs in combination with the mutation status of the c-KIT gene." (PMID 35720122, 2022). "In addition to the first mutation on exon 11, a secondary alteration on KIT was detected in three patients with metastatic disease." (PMID 26544626, 2015). "Additionally, the surgically primary tumor specimen and the metastatic tumor specimen were sequenced, and it was discovered that mutations of c-KIT c.1668_1679delGTGGAAGGTTGT in exon 11 and c.1926delA in exon 13 were present in both the surgically primary and metastatic tumors (respectively)." (PMID 35720122, 2022). "detected KIT mutations in 15.8% (22/139) of their OMM cohort and associated these mutations with a poorer prognosis in metastatic disease." (PMID 40344340, 2025). "The recommended management of solitary GIST is surgery, while larger or metastatic tumors that express c-KIT are managed with imatinib as either neoadjuvant or adjuvant therapy." (PMID 36874698, 2023). "Although all of them are sensitive to first-line imatinib, KIT exon 11-mutants are more sensitive than exon 9, and the latter commonly requires double dose of imatinib for metastatic disease." (PMID 37129716, 2023). "In terms of metastatic disease, previous studies have addressed the predictive role of KIT exon 11 PVs on response and survival to imatinib." (PMID 33673554, 2021). "GIST represents a model disease of oncogenic dependency on receptor tyrosine kinases, as evidenced by long-lasting remissions during KIT-inhibitory treatment even in patients with widely metastatic disease." (PMID 25781619, 2015). "Our study confirms the presence of DMD deletions only in KIT/PDGFRA mutant GIST and this event is almost associated with metastatic disease." (PMID 25143820, 2014). "Identification of a distinctive molecular signature involving KIT or PDGFRA mutations allowed targeted therapies in patients with metastatic disease, who did not have effective therapeutic options until then." (PMID 20470368, 2010). "However, additional events besides primary KIT mutations are needed for GIST cells to evolve into metastatic or resistant disease, as evidenced by similar or identical KIT mutations in cases of micro-GISTs and metastatic tumors." (PMID 30867899, 2019).
metastatic disease (continued). "In addition to the first mutation, a secondary alteration on KIT was detected in three patients with metastatic disease and in none of the patients with localized tumors." (PMID 26544626, 2015). "Overall, while most alterations overlapped between primary and metastatic tumors, the enrichment of BRD4 in metastatic disease and KIT in primary tumors suggest potentially meaningful differences in progression that should be confirmed in independent datasets." (PMID 41154418, 2025). "Evaluation of stem/progenitor marker expression on cytokeratin+ cells from normal lung, untreated KIT+ and KIT- primary NSCLC, and recurrent metastatic disease presents the opportunity to correlate the presence of these markers with disease progression." (PMID 23285214, 2012).
mucosal (40 papers, 2008 to 2025). "KIT mutations were present in one cutaneous and two mucosal tumors." (PMID 30188888, 2018).
prostate carcinoma (39 papers, 2008 to 2026). A carcinoma that arises from epithelial cells of the prostate gland. "Transfection of tr-KIT into prostate cancer cells caused a dramatic increase in Src activity." (PMID 24709904, 2014). "Abnormal expression of KITLG and its receptor KIT has been reported in multiple epithelial-derived cancers, including breast, lung, and prostate cancers." (PMID 40781225, 2025). "Another study identified a rare prostate cancer stem cell maker, KIT Proto-Oncogene, Receptor Tyrosine Kinase (KIT) in adult mouse prostatic stem cell population, which possess cancer stem cell-like features such as differentiation and self-renewal." (PMID 35800367, 2022). "A positive correlation between the number of Ki67-positive cells and c-KIT transcript levels was observed in prostate cancer samples." (PMID 29207991, 2017). "Furthermore, the expressions of CLU, TUBA4A, and KIT were successfully validated in collected prostate cancer tissue samples." (PMID 42317356, 2026). "Except for KIT, the remaining genes were investigated as possible prostate cancer therapy genes." (PMID 36376815, 2022). "Four normal prostates, 4 PIA and 5 prostatic carcinomas showed positive c-KIT expression." (PMID 29207991, 2017). "This study assessed c-KIT and Ki67 expression in canine prostate cancer (PC)." (PMID 29207991, 2017). "c-KIT expression has been related to bone metastasis in human prostate cancer, but whether c-KIT expression can be similarly classified in canine prostatic tissue is unknown." (PMID 29207991, 2017). "Additionally, we have investigated c-KIT protein expression by immunoblotting in two primary canine prostate cancer cell lines." (PMID 29207991, 2017). "Therefore, c-KIT heterogeneous protein expression among the samples (five positive and thirteen negative prostate cancer samples) indicates a personalized approach for canine prostate cancer." (PMID 29207991, 2017). "The median relative quantification (RQ) for c-KIT expression in normal, PIA and prostate cancer and metastatic samples were 0.6 (0.1-2.5), 0.7 (0.09-2.1), 0.7 (0.09-5.1) and 0.1 (0.07-0.6), respectively." (PMID 29207991, 2017). "Several are known biomarkers for diagnosis and prognosis of prostate cancer (APC, GSTP1, KIT, PYCARD, PGDGRB, RARB, RARRES1, and TIMP1) and some though not biomarkers, were found to be dysregulated in the disease (CDKN1B, MMP7, and MMP9)." (PMID 24626295, 2014). "The enriched genes included CD4 in cervical cancer, VPS52, NUP62, CRYGD, IL34, GATA3 in prostate cancer and F11, TXNIP, KIT, ASGR2, SERPINF1 in liver cancer, which also provide insight into the molecular mechanisms underlying cancer progression and the potential impact on patient survival." (PMID 37393582, 2023). "Prostate cancer cell lines and tumors expressing the tr-KIT have higher levels of phosphorylated/activated Src than tr-KIT-negative cells and tumors." (PMID 24709904, 2014). "Han identified significant activation of the FOXA2-KIT signaling axis in t-NEPC, identifying the KIT signaling pathway as a therapeutic target for NEPC, but current clinical trials of KIT inhibitors in prostate cancer have not reached valid endpoints (phase III)." (PMID 39655078, 2024). "Furthermore, the α155 and HMC1.2 cell lines, whose growth strictly depends on c-KIT, showed a high sensitivity to AQ1 while the prostate cancer cell line PC3 did not." (PMID 26942875, 2016).